LCK (LCK proto-oncogene, Src family tyrosine kinase)
Diseases named in the same sentence as LCK in open-access papers (continued):
Sharing a sentence is not in itself a finding about the gene and the disease.
cancer (continued). "Next, we analyzed the TIL-B and TIL-T abundances using the CD20 and LCK protein levels in the TCGA RPPA dataset, including 7,694 primary cancer tissues across 32 cancer types." (PMID 35069521, 2021). "In the direct comparisons across 32 cancer types, the expression levels of CD20 and LCK in DLBC (lymphoid neoplasm diffuse large B cell lymphoma) were first and second-highest, respectively, which were attributed to the tissue origins related to B and T cells." (PMID 35069521, 2021). "To investigate this phenomenon across different cancer and tissue types, we compared the correlations between the mRNA and protein levels of CD20 and LCK in the TCGA and CCLE datasets." (PMID 35069521, 2021). "In the TCGA RPPA data of approximately 200 proteins across 32 cancer types, the most probable cell markers for B and T cells were CD20 and LCK." (PMID 35069521, 2021). "CD8+ T cells and macrophage M1 are more abundant in favor of a higher expression of CD3E and LCK in MIBC and across pan-cancers." (PMID 35004669, 2021). "Next, in the Cancer Cell Line Encyclopedia (CCLE) RPPA dataset, we found that the CD20 and LCK proteins expressed dominantly in cell lines derived from the hematopoietic and lymphoid tissues (upper plots)." (PMID 35069521, 2021). "Following this idea, we performed a preliminary analysis in which we correlated LCK and SRC mRNA expression in about 500 human cancer cell lines with the metastatic potential of the respective cells." (PMID 34116687, 2021). "Cross-cancer alteration analysis for Abl-1, EGFR, Fyn, LCK, Src, ACK1 (TNK2) tyrosine kinases reveal that these genes are frequently altered in cancers, e.g. EGFR and TNK2 are recurrently amplified and mutually exclusive in a majority of the cancer cases." (PMID 26546517, 2015). "Because LCK enhances uPA and MMP9 expression resulting in cancer invasion and metastasis, the effect of FOXP3 WT and Y342F mutation on LCK-induced invasion was investigated." (PMID 24155921, 2013). "Furthermore, LCK, Perforin, and CD38 were identified as potential prognostic IHC biomarkers and should be evaluated in larger patient cohorts of both precancer and cancer patients." (PMID 34830895, 2021). "These analyses are important in order to develop cancer-specific LCK inhibitors that do not interfere with immune cell functions by blocking LCK signaling in lymphocytes." (PMID 34116687, 2021). "Moreover, we presented the summary plots that include the significant prognostic relevance of LCK and CD20 for individual cancer types and subgroups." (PMID 35069521, 2021). "Moreover, this positive correlation between memory B cell, CD8+ T cell, CD4+ memory activated, and macrophage M1 with LCK and CD3E was also consistent across different cancer types." (PMID 35004669, 2021). "The LCK and TEC kinases identified in the present study may also play a role in the anti-cancer immune response elicited and frequently evaded by PDAC." (PMID 33213062, 2020). "However, there was no thorough paper about ITGB2-AS1, except that ITGB2-AS1 was reported to have high co-expression with multiple cancer genes (IKZF1, LCK, and WAS)." (PMID 29941860, 2018). "Although previous efforts identified CD55 as a prognostic marker in several cancers, our data provide mechanistic insight into a bifurcating signaling network that regulates self-renewal via ROR2/JNK signaling and cisplatin resistance via LCK signaling." (PMID 28838952, 2017). "However, the cellular and molecular functions of LCK in cancer metastasis and cell motility are not fully understood yet." (PMID 34116687, 2021). "Furthermore, we found that LCK was significantly correlated with TIGIT (total rho=0.82), CTLA4 (total rho=0.77), and PD-1 (total rho=0.81) in most cancer types, indicating the important role of TIGIT, CTLA4, and PD-1 in the TIL-T cells across cancer types." (PMID 35069521, 2021). "So far, LCK expression has not been described in cervical precursor nor cancer lesions." (PMID 34830895, 2021).
cancer (continued). "Thus, LCK peptides, especially those derived from the C-terminal region (LCK486–494 (TFDYLRSVL) and LCK488–497 (DYLRSVLEDF), could be useful in developing a specific immunotherapy for cancer patients with distant metastases." (PMID 34116687, 2021). "These preliminary findings further imply a critical role of LCK in cancer metastasis and suggest a “division of labor” among both tyrosine kinases, whose differential activities or expression patterns might contribute to the observed organotropism of HNSCC-derived cancer cells." (PMID 34116687, 2021).
infection (12 papers, 2013 to 2024). The state of being infected such as from the introduction of a foreign agent such as serum, vaccine, antigenic substance or organism. "To elucidate the role of CD8-bound LCK in the antigenic response in vivo, we adoptively transferred the Lck-variant OT-I T cells into congenic Ly5.1 mice followed by infection with transgenic Listeria monocytogenes (Lm) expressing OVA or its lower-affinity APLs." (PMID 36564464, 2023). "The specific inhibition of co-receptor-bound LCK should impair autoimmune T cell clones with relatively low antigen affinity without inhibiting protective high-affinity T cell responses to infections." (PMID 36564464, 2023). "Deficiencies in CD4, LCK, LAT and ITK have all been associated with immunodeficiency syndromes and an increased risk of childhood infections, highlighting their importance in determining infection risk." (PMID 35608955, 2022). "We have perturbed the concentrations of the signaling molecules, viz., ZAP70, LCK and FYN, which are responsible for stimulating the TCR signaling pathway upon infection." (PMID 24324645, 2013). "After infection, MP antigens stimulate and upregulate T cell surface molecules including CD3D, CD3E, CD3G, and CD8, followed by the upregulation of downstream molecules including CD3Z, FYN, LCK, ZAP70, GADS, P38, and ITK." (PMID 29967623, 2018). "SA2 infection negatively regulated expression of genes like b-arrestin (ARRB2), integrinAε (ITGAE), hemolytic complement (HC), lymphocyte protein tyrosine kinase (LCK) that are involved in pathogen clearance or induction of immune response." (PMID 25075227, 2014).
hematologic malignancies (4 papers, 2021 to 2023). "Lymphocyte-specific protein tyrosine kinase (LCK) is common in a variety of hematologic malignancies but comparatively less common in solid tumors." (PMID 36430477, 2022). "Owing to the important role of LCK in immune cell responses, numerous studies have explored the functions and therapeutic values of LCK in hematologic malignancy." (PMID 36430477, 2022).
cardiovascular disease (2 papers, 2019 to 2020). "Interestingly it is known that LCK, LYN, and FYN are part of the SRC-family kinases (SFKs) and have been associated with various aspects of cardiovascular disease." (PMID 30717456, 2019).
blood cancer (1 paper, 2018). "For example, LCK was highly expressed only in a subset of blood cancer cell lines concordant with its specific roles in T cell development." (PMID 29293502, 2018).
hematopoietic cancer (1 paper, 2024). "Furthermore, we found that expression levels of ZAP70, FYN, GRAP2, ITK, and LCK as well as two further TCR pathway kinases, PLCG1 and LAT, were highest in human T-ALL cell lines compared with other hematopoietic cancer lines." (PMID 38618957, 2024).
LCK also shares sentences with these, for which no sentence is quoted: rheumatoid arthritis (4 papers); Zinc deficiency (3); alveolar rhabdomyosarcoma (2); Arthritis (2); bile duct cancer (2); esophageal carcinoma (2); metastatic tumors (2); pneumonia (2); stomach adenocarcinoma (2); adenocarcinoma (1); adult T-cell leukemia/lymphoma (1); alveolar soft part sarcoma (1); ataxia telangiectasia (1); atopic dermatitis (1); Beckwith-Wiedemann syndrome (1); Behçet disease (1); bladder tumors (1); bone marrow cancer (1); brain tumors (1); childhood asthma (1); chordoma (1); chronic hepatitis C (1); Clouston syndrome (1); CNS DLBCL (1); coinfection (1); colorectal (1); dermatomyositis (1); dysplasia (1); epidermodysplasia verruciformis (1); Ewing sarcoma (1).
A further 45 diseases each share a sentence with LCK in 1 paper.